NUAK1 (NUAK family kinase 1)
Diseases named in the same sentence as NUAK1 in open-access papers (continued):
Sharing a sentence is not in itself a finding about the gene and the disease.
tumor (continued). "We used OVCAR8, OVCAR3, and HEYA8 to further investigate this function of NUAK1 in EOC metastasis, because they readily form spheroids in vitro and can establish xenografted tumours when injected intraperitoneally into immune-compromised mice." (PMID 32429240, 2020). "Finally, we sought whether LKB1 regulates NUAK1 expression in tumours." (PMID 32429240, 2020). "In this study, we proposed an effective combination strategy of dual inhibition of NUAK1 and ULK1 kinase activities, which was proved to have a synergetic cytotoxic effect on tumor cells, which promotes apoptosis and elevated levels of ROS." (PMID 32873786, 2020). "Calcium/PKCα-dependent activation of NUAK1 supports engagement of the AMPK-TORC1 metabolic checkpoint, thereby protecting tumour cells from MYC-driven cell death, and indeed, MYC selects for this pathway in part via transcriptional regulation of PKCα and ITPR." (PMID 29106388, 2018). "Furthermore, we detected the expression of NUAK1 and PD-L1 in HCC patients by IHC staining, and found that tumor tissues with high NUAK1 expression also had high PD-L1 expression." (PMID 39901136, 2025). "Our study revealed that miR-1182 and let-7a could play a role as tumor suppressors in CCA through the disruption of cell migration, invasion, proliferation, and autophagy by down-regulating NUAK1 expression." (PMID 33750398, 2021). "As a member of the human adenosine monophosphate-activated protein kinases family, NUAK1 (also known as ARK5, AMPK-related kinase 5) has been observed to have a high expression in multiple human malignancies, and participates in tumor invasion, migration, survival and progression." (PMID 33750398, 2021). "Additionally, we describe two main AMPK-related kinases, Novel (nua) kinase family 1 (NUAK1) and 2 (NUAK2), which have been understudied, but play a major role in cellular physiology and tumor development." (PMID 34685740, 2021). "Moreover, NUAK1 silencing reduces the invasive capacity of HCC and GC cells in vitro and reduces tumor formation in vivo." (PMID 34685740, 2021). "The role of NUAK1 and NUAK2 in cancer has been observed across various tumor types." (PMID 34685740, 2021). "Overall, evidence suggests that NUAK1 and NUAK2 play an important role in tumor development as protein kinases and could be appealing therapeutic targets." (PMID 34685740, 2021). "Additionally, NUAK1 and NUAK2 overexpression has been found in various tumor types and their upregulation is often correlated with an increased migration and invasion capacity." (PMID 34685740, 2021). "Thus, the combined inhibition of NUAK1 and ULK1 showed a strong synergistic effect in different tumor types." (PMID 32873786, 2020). "When NUAK1 is transfected into OSCC cells, tumor invasion increased." (PMID 30901831, 2019). "Furthermore, when NUAK1 was activated by PKC, it protected MYC-driven tumor cells from cell death." (PMID 34282782, 2021). "Additionally, we showed that xenografted tumours lacking NUAK1 had decreased fibronectin expression, and this was complemented by a strong positive correlation between NUAK1 and FN1 in serous EOC tumours from patients." (PMID 32429240, 2020). "Two methods of NUAK1 activation have been reported: a tumor suppressor LKB1-dependent NUAK1 activation; in cells lacking LKB1 38, modulation of NUAK1 activity through the calcium-dependent PKC pathway." (PMID 37576402, 2023). "Here we show that, in tumour cells lacking LKB1, NUAK1 activity is maintained by an alternative pathway involving calcium-dependent activation of PKCα." (PMID 29106388, 2018).
cancer (52 papers, 2014 to 2025). A tumor composed of atypical neoplastic, often pleomorphic cells that invade other tissues. "The vast majority are reportedly linked to NUAK1’s roles in cancer cell migration, epithelial to mesenchymal transition and/or metastasis, e.g., miR203, miR204, and miR211." (PMID 38939918, 2024). "The loss of NUAK1 expression induces apoptosis in cancer cells with over-expression of MYC, a commonly observed phenotype of tumorigenesis." (PMID 38434478, 2024). "NUAK1 has been reported highly expressed in many human cancers and is associated with the poor prognosis of cancer patients." (PMID 37919754, 2023). "Overexpression of NUAK1 is associated with poor prognosis in many cancers, including colorectal, ovarian, and lung." (PMID 34504167, 2021). "On the contrary, our data propose that the cytosolic NUAK1 maintains glycolytic capacity and the glycolysis-associated cell energy in the abnormal genetic and metabolic context of cancer." (PMID 32754444, 2020). "Elevated NUAK1 is closely associated with cancer metastasis and patient survival via epithelial–mesenchymal transition (EMT) alteration." (PMID 32873786, 2020). "NUAK1 has a critical role in the adaptive antioxidant response, which is associated with aggressive cancer and worse outcome." (PMID 32873786, 2020). "Accordingly, NUAK1 was associated with metastasis because it promotes cell migration and invasion in different cancer cells." (PMID 32754444, 2020). "In the context of PTEN-deficiency, AKT phosphorylation of NUAK1 at Ser-600 promotes proliferation and invasion in cancer cell lines." (PMID 29566768, 2018). "Supporting the role of NUAK1/ARK5 in the aggressive cancer phenotype, this gene was independently associated with decreased survival (HR = 1.34, 95 % CI 1.16–1.56)." (PMID 27756408, 2016). "Others and our studies indicate that NUAK1 distribution is cell- and context-specific, and might be associated with the clinical stage of cancer, displaying a cytosolic accumulation in late-stages histopathological samples." (PMID 32754444, 2020). "Altogether, our results suggest that the cytosolic NUAK1 associated with cancer cell bioenergetics." (PMID 32754444, 2020). "Recently, several important studies have highlighted that NUAK1, as a key component of the antioxidant response pathway, is associated with aggressive disease and poor outcome in cancer patients through suppressing Gsk3β-dependent inhibition of NRF2 nuclear localization." (PMID 32873786, 2020). "We demonstrated that cytosolic NUAK1 increases ATP levels, which associates with increased mitochondrial respiration, supporting that cytosolic NUAK1 is involved in mitochondrial function regulation in cancer cells." (PMID 32754444, 2020). "Overall, our findings corroborate previous evidence that has implicated NUAK1 as a key factor underlying poor disease prognosis in diverse cancer subtypes and expand on recent precedents associating NUAK1 transcript expression with poor outcome in HGSOC patients." (PMID 27833898, 2016). "Thus, we investigated whether a combined inhibition of NUAK1 and mTOR may be an approach to avoid Akt reactivation, causing cancer cell death." (PMID 38135881, 2023). "Thus, NUAK1-dependent metabolic effects may explain the aggressiveness of cancers associated with abnormal NUAK1 expression." (PMID 32754444, 2020). "In light of this, we aimed at testing a potential role of NUAK1 in controlling mitochondrial metabolism, as recently shown in cancer models." (PMID 38514619, 2024). "In cancer cells, NUAK1 overexpression enhances mitochondrial ATP production, while proteomic analysis following depletion of NUAK1 revealed reduced expression of multiple nuclear-encoded electron transport chain (ETC) proteins." (PMID 38939918, 2024).
cancer (continued). "According to GSEA analysis, NUAK1 was enriched in 29 different biochemical processes, including human immunodeficiency virus 1 infection, transcriptional dysregulation in cancer, Th1 and Th2 cell differentiation and PD-L1 expression." (PMID 38774751, 2024). "In parallel, c-Myc overexpressing cancer cells rely on NUAK1 expression to maintain metabolic homeostasis and for survival, suggesting a metabolic role for NUAK1." (PMID 38514619, 2024). "Recently, new drugs or multi-kinase inhibitors targeting NUAK1 plus other kinases were developed, suggesting that NUAK1 is an attractive target for cancer therapy." (PMID 38135881, 2023). "The correlation analyses using TCGA data suggested that the NUAK1/Akt axis is conserved in several types of cancer." (PMID 38135881, 2023). "In other cancers, NUAK1 expression also positively correlates with EGFR expression and Akt Ser-473 phosphorylation." (PMID 38135881, 2023). "Analysis of TCGA datasets via CBioPortal revealed PDAC has the highest average expression of NUAK1 across multiple cancer types." (PMID 36975767, 2023). "Based on the new mechanisms described and their apparent conservation in several types of cancer, we explored combined NUAK1 and Akt or mTOR inhibition to avoid compensatory mechanisms that result in cancer cell survival and resistance to chemotherapy." (PMID 38135881, 2023). "Together with our studies, they point to NUAK1 as a potential target for those cancers with deregulated Akt signaling." (PMID 38135881, 2023). "miR-622 inhibited the GA cancer cell growth occurrence of GC by inhibiting the expression of NUAK1 and counteracting its cancer-promoting effects." (PMID 35872695, 2022). "NUAK1 overexpression correlates with nuclear factor erythroid 2-related factor 2 (NRF2) inhibition in different cancer cell lines." (PMID 34685740, 2021). "There is growing evidence showing NUAK1 is a target of multiple miRNAs, whose expression is frequently decreased during cancer progression to metastatic disease." (PMID 34504167, 2021). "The research of homology modeling and molecular docking provides the foundation for further development of specific NUAK1 inhibitors for the treatment of different types of cancer." (PMID 32873786, 2020). "Depletion of NUAK1 in some cancer cells induces ROS-induced cell death; likewise, elevated oxidative stress activates the NUAK1-dependent antioxidant pathway to escape from cell death." (PMID 32873786, 2020). "Previous research verified that MYPT1/Gsk3β is the critical substrate of NUAK1 kinase that protects cancer cells from oxidative stress." (PMID 32873786, 2020). "NUAK1 promotes epithelial-to-mesenchymal transition (EMT) in cancer and induces cell detachment by regulating the MYPT-PP1β complex." (PMID 32429240, 2020). "We have previously found that endogenous NUAK1 has a diverse subcellular localization depending on the cancer cell line, mostly located in the nucleus or the cytoplasm, or with an equilibrated distribution." (PMID 32754444, 2020). "Previous studies and data in CCLE (Cancer Cell Line Encyclopedia) suggest that NUAK1 is overexpressed in many solid tumor cell lines." (PMID 32873786, 2020). "NUAK1 showed different cell distribution in cancer samples, where cytosolic NUAK1 seems to be relevant in late-stages of cancer." (PMID 32754444, 2020). "In summary, our study has demonstrated a new therapeutic strategy for inhibiting cancer growth with dual-targeting antioxidant mechanisms and mitophagy using a NUAK1/ULK1 dual inhibitor, MRT68921." (PMID 32873786, 2020). "Elevated NUAK1 expression in different cancer types represents worse malignant behaviors, including chemotherapeutic resistance, early-stage metastasis, and poorer outcome." (PMID 32873786, 2020).
cancer (continued). "NUAK1 has been described as a predominantly nuclear protein in some cancer cells, where it promotes spliceosome activity and regulates RNA synthesis." (PMID 32754444, 2020). "Because metabolic changes in cancer cells are balanced between glycolysis and oxidative metabolism, the study indicated that NUAK1 keeps cells metabolically prepared to face microenvironmental energetic adversities." (PMID 32754444, 2020). "Altogether, our results suggest that cytosolic NUAK1 participates in mitochondrial ATP production and the maintenance of proper glycolysis in cancer cells." (PMID 32754444, 2020). "The cytotoxic effect of MRT68921 in the tested cancer cell lines was found to be superior to reported NUAK1 inhibitors WZ4003 and HTH-01-015." (PMID 32873786, 2020). "NUAK1 promotes cancer cell survival by inhibiting apoptosis and inducing the S-phase in the cell cycle." (PMID 32429240, 2020). "Despite accumulating evidence revealed the direct role of NUAK1 on cancer cell proliferation, migration and drug resistance, it is still unknown whether NUAK1 contributes to immune escape in HCC." (PMID 39901136, 2025). "Although the direct roles of NUAK1 on cancer cell proliferation and migration were determined in HCC, the underlying mechanisms remains largely unknown." (PMID 39901136, 2025). "In addition, the over-expression of NUAK1 in the cytoplasm supports glycolytic switch of cancer cells." (PMID 38434478, 2024). "Others, such as miR96, miR145 and miR143 link NUAK1 or NUAK2 to more general roles in cancer." (PMID 38939918, 2024). "Because NUAK1 inhibition synergies with Akt or mTOR blockage, we investigated the cancers where co-targeting may be used." (PMID 38135881, 2023). "To determine if the effect of NUAK1 suppression on centrosome number was cancer cell‐specific, we used floxed Nuak1fl/fl MEFs stably expressing 4‐OH‐Tamoxifen‐inducible CRE recombinase fused to the modified ligand binding domain of the oestrogen receptor, CRE‐ERT2." (PMID 36975767, 2023). "To validate the relevance of the identified NUAK1/Akt axis, we investigated whether NUAK1 expression correlates with the expression of upstream modulators of Akt signaling and Akt phosphorylation in human cancers." (PMID 38135881, 2023). "Moreover, NUAK1 mRNA is targeted by several microRNAs that reduce cancer cell migration and/or proliferation in a spectrum of cancer types." (PMID 36975767, 2023). "Due to the new role of NUAK1 in regulating the Akt signaling and mTOR, we asked whether a combined inhibition of NUAK1 and Akt or mTOR may benefit cancer therapy." (PMID 38135881, 2023). "Similar results were observed in other cancer cell lines using the NUAK1 inhibitor." (PMID 38135881, 2023). "Unlike canonical oncogenes, NUAK1 is rarely mutated in cancer and appears to function as an obligate facilitator rather than a cancer driver per se." (PMID 36975767, 2023). "Survival meta-analysis showed that NUAK1, Akt isoforms (Akt1, Akt2, and Akt3), mTOR, and Rictor positively correlate with a high hazard ratio (HR) in BRCA, COAD, GBM, PRAD, STAD, and OV, the same types of cancer where NUAK1 correlates with EGFR expression and Akt Ser-473 phosphorylation." (PMID 38135881, 2023). "Recently, new evidence suggested a critical role of NUAK1 in cancer cell signaling." (PMID 38135881, 2023). "As a serine/threonine kinase, NUAK1 has been shown to play an oncogene in various human cancers." (PMID 37919754, 2023). "Because of the relevance of the Akt/FOXO pathway in the regulation of cell cycle, senescence, and cancer cell survival, we investigated whether NUAK1 regulates these processes under growth factor stimulation." (PMID 38135881, 2023). "Therefore, our study provides a rationale to explore the potential therapeutic outcome of NUAK1 inhibition and additional combinations with Akt or mTOR inhibitors in several types of cancer." (PMID 38135881, 2023).
cancer (continued). "Although the mechanism was unknown, previous studies demonstrated that NUAK1 promotes cancer cell proliferation and survival." (PMID 38135881, 2023). "Our findings warrant further investigation to determine whether targeting NUAK1 can enhance the effectiveness of therapeutic strategies that benefit from ROS induction in cancer cells." (PMID 35194062, 2022). "NUAK1 promotes motility, invasion, and metastases of cancer cells." (PMID 36295658, 2022). "The 3′UTR of NUAK1 has been shown to be targeted by multiple deregulated miRNAs in several cancers." (PMID 35872695, 2022). "We were unable to find NUAK1 overexpression-induced changes in the mitochondrial volume; however, we cannot exclude that sustained NUAK1 overexpression, common in many cancers, could affect it." (PMID 32754444, 2020). "Many studies have reported that NUAK1 is critical for the survival of cancer patients." (PMID 32873786, 2020). "The 3’UTR of NUAK1 is a target of multiple miRNAs deregulated in different types of human cancers." (PMID 32418991, 2020). "Cancer cell survival is also promoted by NUAK1 through altered metabolic homeostasis." (PMID 32429240, 2020). "Our studies indicate that NUAK1 plays a role in the maintenance of glycolytic and respiratory capacities of cancer cells, suggesting that it affects the metabolic state and adaptation of tumors during cancer progression." (PMID 32754444, 2020). "Additionally, NUAK1 plays a role in the survival of cancer cells, protecting them from cell death induced by oxidative or metabolic stress." (PMID 32754444, 2020). "Still, because NUAK1 protected cells from oncogenic MYC-induced metabolic stress and energy collapse, NUAK1 is also likely downstream of other oncogenes-induced metabolic stress, the hallmark of any cancer." (PMID 32754444, 2020). "Besides, NUAK1 supports cancer cell survival under metabolic stress and maintains ATP levels in hepatocarcinoma cells, suggesting a role in energy metabolism in cancer." (PMID 32754444, 2020). "Additionally, our results indicated that cytosolic NUAK1 increases the glycolytic capacity of cancer cells under mitochondrial inhibition." (PMID 32754444, 2020). "Accordingly, it has been suggested that AICAR could increase the activity of NUAK1 in cancer cells." (PMID 38514619, 2024). "Therefore, these analyses strongly suggest that NUAK1 is associated with the Akt activation downstream of the EGF-signaling in human cancers, supporting further studies to investigate whether targeting the NUAK1/Akt axis could be therapeutically beneficial." (PMID 38135881, 2023). "Therefore, targeting NUAK1 or combined inhibition with Akt or mTOR inhibitors may be considered in cancer treatments." (PMID 38135881, 2023). "All these results confirmed that NUAK1 impacts cancer cell survival, indicating that its inhibition, either alone or combined with other drugs that block Akt or mTOR activity, could be a therapeutic strategy in cancers with hyperactivated Akt signaling." (PMID 38135881, 2023). "In addition, our studies identified a mechanism by which NUAK1 may promote cancer cell survival and proliferation." (PMID 38135881, 2023). "Therefore, targeting NUAK1, or co-targeting it with Akt or mTOR inhibitors, may be effective in cancers with hyperactivated Akt signaling." (PMID 38135881, 2023). "Thus, we identified a novel NUAK1/Akt/FOXO1-3a axis, which may be implicated in cancer progression and chemotherapy efficacy." (PMID 38135881, 2023). "Therefore, screening NUAK1 cell distribution in cancer tissues could help elucidate the metabolic state of tumors." (PMID 32754444, 2020). "Therefore, NUAK1 is considered an attractive therapeutic target in cancer." (PMID 32873786, 2020). "Therefore, we hypothesize that STK11 and NUAK1 are selectively essential for cell cycle progression and DNA damage repair in PTEN-deficient cancers." (PMID 29566768, 2018). "Thus, the contribution of NUAK1 in other cancers requires further examination." (PMID 30158528, 2018).